RAB1A (RAB1A, member RAS oncogene family)
Diseases named in the same sentence as RAB1A in open-access papers (continued):
Sharing a sentence is not in itself a finding about the gene and the disease.
prostate carcinoma (9 papers, 2016 to 2023). A carcinoma that arises from epithelial cells of the prostate gland. "Taken together, SGOL2 was a novel regulator of RAB1A to regulate prostate cancer development in vitro." (PMID 36566018, 2022). "In conclusion, our findings concluded that SGOL2 stabilized RAB1A expression to promote prostate cancer development." (PMID 36566018, 2022). "GEPIA 2.0 represented a moderate correlation between SGOL2 and RAB1A in prostate cancer, consistent with mass spectrometry prediction." (PMID 36566018, 2022). "Rescue Experiments demonstrated that SGOL2 promoted prostate cancer cell proliferation and migration by upregulating RAB1A expression." (PMID 36566018, 2022). "Mass spectrometry, correlation analysis, and Co-IP jointly confirmed that SGOL2 played a critical role in RAB1A regulation in prostate cancer." (PMID 36566018, 2022). "We further investigated the role of SGOL2 in the regulatory mechanism of RAB1A in prostate cancer cell lines." (PMID 36566018, 2022). "On the other hand, it was reported that Rab1A expression was reduced in androgen-independent prostate cancer and Rab1A depletion enhanced the proliferation ability of prostate cancer cells." (PMID 34376787, 2021). "Recent reports have shown that knockdown of Rab1a in prostate cancer cells suppresses cell adhesion." (PMID 34068233, 2021). "On the other hand, some studies reported that reduced expression of Rab1A was observed in androgen-independent prostate cancer, and knockdown Rab1A enhanced the proliferation ability of prostate cancer cells." (PMID 33068388, 2020). "Generally, our data demonstrated that SGOL2 and RAB1A might be used to detect cancer progression and act as potential therapeutic targets in prostate cancer." (PMID 36566018, 2022). "Finally, based on our bioinformatic findings, we conjectured that SGOL2 and RAB1A both contributed to tumor microenvironment (TME) modulation in prostate cancer." (PMID 36566018, 2022). "RAB1A overexpression promoted prostate cancer cell proliferation." (PMID 36566018, 2022). "Results presented that SGOL2 and RAB1A may regulate the TME in prostate cancer." (PMID 36566018, 2022). "Finally, we found that SGOL2 and RAB1A may regulate the tumor microenvironment (TME) in prostate cancer." (PMID 36566018, 2022). "Our findings indicated that SGOL2 probably stabilized RAB1A to regulate TME and this result contributed to our understanding of prostate cancer." (PMID 36566018, 2022). "In order to confirm the role of SGOL2/RAB1A regulatory axis in prostate cancer, we constructed four cell models using SGOL2 knockdown lentivirus and RAB1A overexpression (OE) lentivirus (control group, shSGOL2 + RAB1A-OE group, shSGOL2 group, RAB1A-OE group)." (PMID 36566018, 2022). "Recent studies have further established Rab1A as an activator of mTORC1 in CRC, prostate cancer and HCC5,11,27, and also shown a crosstalk between mTOR/S6K1 and Gli128–30." (PMID 31527621, 2019). "At last, we speculated both SGOL2 and RAB1A were involved in modulating TME, which provided a direction to develop the efficiency of prostate cancer treatment." (PMID 36566018, 2022). "To figure out whether SGOL2 and RAB1A influence TME in prostate cancer, we downloaded the dataset of prostate cancer patients (n=450) from the TCGA database." (PMID 36566018, 2022).
Parkinson disease (7 papers, 2020 to 2024). A progressive degenerative disorder of the central nervous system characterized by loss of dopamine producing neurons in the substantia nigra and the presence of Lewy bodies in the substantia nigra and locus coeruleus. "The abnormal expression of RAB1A has been associated with many human diseases, such as glucose homeostasis, Parkinson’s disease and various cancers." (PMID 38436022, 2024). "Rab1a represents an important therapeutic target as it has been implicated in the pathogenesis of several human diseases such as cardiomyopathy, Parkinson’s disease and cancer." (PMID 31973201, 2020). "Aberrant Rab1A expression has been linked to a range of human diseases such as Parkinson's disease and cardiomyopathy." (PMID 33214609, 2020). "Beyond cancer, Rab1a proteins play a causal role in the pathogenesis of several human diseases such as cardiomyopathy and Parkinson’s disease." (PMID 31973201, 2020). "The complex regulation of Rab1 GTPases and their impact on Golgi dynamics, tau secretion in Alzheimer’s disease, and motor function in Parkinson’s disease underscore the therapeutic promise of targeting Rab1A in neurodegenerative processes." (PMID 39600882, 2024). "In contrast, only Rab1A, and not Rab1B, has been associated with neurological disorders, for example, Parkinson’s disease, Alzheimer’s disease, amyotrophic lateral sclerosis, and intellectual disability." (PMID 36781179, 2023).
bladder cancer (6 papers, 2020 to 2025). "MNX1-AS1 contributed to bladder cancer initiation and progression via the modulation of miR-218-5p/RAB1A pathway." (PMID 33882027, 2021). "MNX1-AS1 regulates the expression of RAB1A in bladder tumor cells by competitively binding with miR-218-5p, thereby promoting the proliferation, migration, invasion, and epithelial-mesenchymal transition of bladder tumor cells, which contributes to the growth and metastasis of bladder cancer cells." (PMID 34490046, 2021). "In bladder cancer, the deubiquitinating enzyme PSMD7 promotes tumor development by stabilizing RAB1A expression." (PMID 40413536, 2025).
breast carcinoma (6 papers, 2021 to 2025). "Our statistical analysis of the expression levels of Parkin, Rab1a, and Rab7a proteins in breast cancer tissues (n = 88) indicated that there were significant reciprocal correlations between Parkin and Rab1a, as well as between Parkin and Rab7a." (PMID 40687836, 2025). "miR-139 has been also reported as a suppressor of invasion and migration in breast cancer cell lines, by targeting RAB1A gene." (PMID 34123357, 2021). "Our findings that Parkin mediates ubiquitination of these oncogenic Rabs and decreases their expression in the cell, as well as the reciprocal correlations between Parkin and Rab1a or Rab7a in breast cancer tissues, reiterate the role of Parkin as a tumor suppressor." (PMID 40687836, 2025).
gastric cancer (5 papers, 2019 to 2024). A primary or metastatic malignant neoplasm involving the stomach. "Taken together, our results demonstrate that C118P causes RAB1A protein degradation via the autophagy–lysosomal pathway in gastric cancer." (PMID 39771598, 2024). "Our current study showed that C118P has a considerable inhibitory effect on gastric cancer via targeting RAB1A, suggesting its potential for cancers with high RAB1A expression." (PMID 39771598, 2024). "Consistently, the results from CETSA showed that C118P (50 nM) increased the thermal stabilization of RAB1A protein in the lysates of gastric cancer cells, suggesting that C118P binds to RAB1A in the cellular context." (PMID 39771598, 2024). "C118P shows potential as being a small molecule drug effective in the treatment of gastric cancer via targeting RAB1A." (PMID 39771598, 2024). "Taken together, our data demonstrate that C118P suppresses the growth of tumors via inhibiting proliferation and inducing apoptosis, as well as targeting the RAB1A-mTOR axis in gastric cancer." (PMID 39771598, 2024). "Our previous study indicates that Rab1A expression is closely related to GLI1 expression in gastric cancer." (PMID 33214609, 2020). "We also validated the role of Rab1A in gastric cancer (GC) patients, and its anti-cancer effects in vitro and in vivo by using the gene knockdown approach in order to identify a novel therapeutic target for GC." (PMID 31527621, 2019). "RAB1A is involved in tumor progression, including the cell cycle, proliferation, and apoptosis, and has been shown to promote tumor growth during carcinogenesis and progression in gastric cancer." (PMID 39771598, 2024). "We further elucidated the contribution of RAB1A to C118P-mediated anti-tumor effects against gastric cancer, which could provide guidance for the rational use of C118P in clinical trials." (PMID 39771598, 2024).
rectal cancer (5 papers, 2015 to 2025). A primary or metastatic malignant neoplasm that affects the rectum. "Various RAB genes have been linked to tumors, including RAB27A, which serves as a predictive indicator for pancreatic ductal adenocarcinoma; RAB13 and RAB3D, which are elevated in pan-cancer; and RAB1A and RAB6A, which have significant functions in rectal cancer and bile duct cancer, respectively." (PMID 40177653, 2025).
colon cancer (4 papers, 2015 to 2022). "In colon cancer cells, Hsc70 prevented proteomic stress-induced degradation of the Ras family member Rab1A and apoptosis." (PMID 34831218, 2021).
tongue cancer (4 papers, 2005 to 2023). A malignant neoplasm affecting the tongue. "We detected a comparatively strong tumour cell-localised cytoplasmic Rab1A-immunoreaction, raising the possibility that the gene product(s) may serve as a diagnostic marker of tongue cancer." (PMID 15870709, 2005). "Another microarray expression profiling of human tongue squamous carcinomas finds that Rab1A is highly expressed in tongue cancer, although the significance of Rab1A overexpression in this particular malignancy remains unknown." (PMID 26308575, 2015).
Alzheimer disease (3 papers, 2023 to 2024). A progressive, neurodegenerative disease characterized by loss of function and death of nerve cells in several areas of the brain leading to loss of cognitive function such as memory and language. "The Rab1A isoform is a key regulator of early endosome sorting and this protein is also thought to be involved in the transport and processing of the APP protein in Alzheimer’s disease." (PMID 38645276, 2024).
cardiac hypertrophy (3 papers, 2015 to 2022). "In the same study, Rab1A transgene is shown to cause cardiac hypertrophy in a gene dosage-dependent manner." (PMID 26308575, 2015). "MiR-101 plays a significant role in hypertrophy by regulating ras-related protein-1A (Rab1A), a member of the Rab family of small GTPases and an important regulator of cardiac hypertrophy." (PMID 30013975, 2018). "In addition, overexpression of miR-101 significantly suppressed AngII-induced cardiac hypertrophy by targeting Rab1A." (PMID 30013975, 2018). "Rab1A overexpression increases Golgi stacks in ventricular myocytes, increases transitional vesicles, and degenerates myelin sheath morphology in atrial myocytes, with abnormal subcellular distribution of PKC, which ultimately leads to cardiac hypertrophy and even heart failure." (PMID 35974003, 2022).
lymph node metastasis (3 papers, 2015 to 2021). "Further analysis showed that Rab1A expression level in human CRC tissues with lymph node metastasis (LNM) was higher than those without LNM (P < 0.01)." (PMID 34376787, 2021).
ovarian carcinoma (3 papers, 2021 to 2023). A malignant neoplasm originating from the surface ovarian epithelium. "One study showed that circ_0061140 conferred tumor malignant development via sponging miR-361-5p and upregulating the RAB1A expression in ovarian cancer cells." (PMID 38152652, 2023). "For example, miR-655-3p inhibited proliferation and migration of ovarian cancer cells by targeting RAB1A." (PMID 35220878, 2022). "Further, circ_0026123 sequestered miR-543 and upregulated RAB1A in ovarian cancer cells." (PMID 38152652, 2023). "Therefore, circ_0026123 elevated the expression of RAB1A via sponging miR-543, leading to promotion of oncogenesis and cisplatin resistance in ovarian cancer." (PMID 38152652, 2023). "Overexpression of RAB1A or knockdown of miR-543 reversed the functions of circ_0026123 knockdown on cisplatin sensitivity and tumor behaviors in DDP-resistant ovarian cancer cells." (PMID 38152652, 2023). "Specifically, miR-655 was markedly decreased in ovarian cancer tissues, and enhancement of miR-655 levels could suppress cell proliferation and invasive ability of SKOV3 cells by directly targeting RAB1A." (PMID 33643926, 2021).
cardiomyopathy (2 papers, 2014 to 2020). A disease of the heart muscle or myocardium proper. "In addition, RAB1A (65M) has been reported to be associated with cardiomyopathy." (PMID 24892410, 2014).
liver cancer (2 papers, 2015 to 2023). An epithelial or non-epithelial malignant neoplasm that arises from the liver. "Our findings further suggest that Rab1A is a valuable biomarker for prognosis and personalized mTORC1-targeted therapy in liver cancer." (PMID 26308575, 2015). "In support of a key role for Rab1A in activation of mTORC1 signaling in liver cancer, Rab1A expression in HCC tissues is generally correlated closely with the level of P-S6K." (PMID 26308575, 2015).
nasopharyngeal carcinoma (2 papers, 2020 to 2024). A carcinoma arising from the nasopharyngeal epithelium. "However, the biological function and molecular mechanism of Rab1A in nasopharyngeal carcinoma (NPC) remained unknown until now." (PMID 33068388, 2020).
neuroblastoma (2 papers, 2016 to 2025). Neuroblastoma (NB) is the most common solid, extracranial childhood tumor. "To investigate this possibility, we quantified the induction of ULK1 complex translocation and autophagy elicited by increased C9orf72S or C9orf72L expression in Rab1a siRNA‐treated HeLa and SH‐SY5Y neuroblastoma cells." (PMID 27334615, 2016).
cerebral infarction (1 paper, 2021). An ischemic condition of the brain, producing a persistent focal neurological deficit in the area of distribution of the cerebral arteries. "In vitro, the expression levels of AT1R, Ang II, Rab1a, Rab1b and VEGF in the cerebral infarction model group were significantly higher than those in the control group, with further increases after administration of FYXN drug serum." (PMID 33679398, 2021). "The results of Western blot showed that upregulating the levels of AT1R, Ang II, Rab1a, Rab1b and VEGF could promote angiogenesis, improve blood supply and alleviate cerebral infarction in MCAO animals." (PMID 33679398, 2021).
colon adenocarcinoma (1 paper, 2019). "Furthermore, increased expression levels of Rab1A resulted in slightly poor overall survival in esophageal carcinoma and colon adenocarcinoma patients." (PMID 31527621, 2019). "Furthermore, Rab1A levels were significantly higher in cholangio carcinoma and pancreatic adenocarcinoma, and moderately higher in the stomach adenocarcinoma, colon adenocarcinoma, rectum adenocarcinoma and liver hepatocellular carcinoma tumors compared to their respective paired normal tissues." (PMID 31527621, 2019).
depression (1 paper, 2022). "In particular, we discovered for the first time that RAB1A, GNAI3, RAB33B, LAMP2, and KIF5B might be potential markers for the diagnosis of depression." (PMID 35559009, 2022).
dilated cardiomyopathy (1 paper, 2015). Cardiomyopathy which is characterized by dilation and contractile dysfunction of the left and right ventricles. "A DNA microarray study in a murine dilated cardiomyopathy model identified Rab1A as one of the highly induced genes during disease progression." (PMID 26308575, 2015).
dysferlinopathy (1 paper, 2023). "Comparative analysis between PM and dysferlinopathy revealed that the DEGs upregulated in PM were most abundant in the protein localization to organelle pathway and helped identify four genes (KDELR3, C0PB2, TMED7, and RAB1A) that were related to ER to Golgi vesicle–mediated transport." (PMID 38125829, 2023).
head and neck squamous cell carcinoma (1 paper, 2020). A squamous cell carcinoma that arises from any of the following anatomic sites: lip and oral cavity, nasal cavity, paranasal sinuses, pharynx, larynx, and salivary glands. "Previous researches have shown that Rab1A expression was significantly upregulated in human head and neck squamous cell carcinoma (HNSCC) and murine fibroblast L929 cells exposed to IR." (PMID 33068388, 2020).
intrahepatic cholangiocarcinoma (1 paper, 2025). A carcinoma that arises from the intrahepatic bile duct epithelium in any site of the intrahepatic biliary tree. "In addition, the previous study has demonstrated that hypoxia-mediated miR-212-3p downregulation enhances the progression of intrahepatic cholangiocarcinoma through the upregulation of Rab1a." (PMID 40565093, 2025).
leukoplakia (1 paper, 2014). A white patch or plaque on a mucous membrane that cannot be characterized clinically or pathologically as any other disease. "Amplification of BTBD7, KHDRBS1, PARP1 and RAB1A was exclusively detected in progressive leukoplakia and corresponding OSCC." (PMID 24403051, 2014). "Interestingly, RAB1A, a member of the RAS oncogene family, which maps to 2p14, was significantly amplified in progressive leukoplakia and OSCC from our data set." (PMID 24403051, 2014). "BTBD7, KHDRBS1, PARP1 and RAB1A were all found to be amplified in progressive leukoplakia lesions and OSSCs and not amplified in non-progressive leukoplakia." (PMID 24403051, 2014). "Amplified genes mapping within recurrent CNAs (KHDRBS1, PARP1, RAB1A, HBEGF, PAIP2, BTBD7) were selected for validation, by quantitative real-time PCR, in an independent set of 32 progressive leukoplakia, 32 OSSCs and 21 non-progressive leukoplakia samples." (PMID 24403051, 2014).
malaria (1 paper, 2012). Malaria is a serious and sometimes fatal disease caused by a parasite that commonly infects a certain type of mosquito which feeds on humans. "The results showed that, compared to the negative control, the live malaria parasite was able to induce an increase in the expression of Rab1a, Rab1b, Rab7a, Rab10, Rab14, Rab20, Rab27a, Rab32 and Rab38." (PMID 22911692, 2012).
melanoma (1 paper, 2021). A malignant, usually aggressive tumor composed of atypical, neoplastic melanocytes. "Other Rab members, Rab1A, Rab5A, Rab7 and Rab27A, have been shown to be highly expressed in melanoma cells." (PMID 34401050, 2021).
nasopharyngitis (1 paper, 2020). An inflammatory process that affects the nasopharynx. "We firstly evaluated the expression of Rab1A in 106 NPC tissues and 54 non-cancerous nasopharyngitis (NP) tissues by immunohistochemistry (IHC)." (PMID 33068388, 2020).
non-small cell lung carcinoma (1 paper, 2023). A group of at least three distinct histological types of lung cancer, including non-small cell squamous cell carcinoma, adenocarcinoma, and large cell carcinoma. "Rab1A was significantly associated with IL4Rα expression in non-small cell lung cancer." (PMID 37117331, 2023). "Recent research reported that Rab1A promotes non-small cell lung cancer metastasis by stabilizing the IL4Rα protein." (PMID 37117331, 2023).
parasite (1 paper, 2021). "The changes in Golgi morphology and subcellular location induced by the loss of GTPase activity (Arf1, Rab1a or Rab11a) and by the parasite infection were visualized by staining against the GM130." (PMID 34013963, 2021).